PRMT1 (protein arginine methyltransferase 1)
Diseases named in the same sentence as PRMT1 in open-access papers (continued):
Sharing a sentence is not in itself a finding about the gene and the disease.
cancer (continued). "However, the function of PRMT1 as a therapeutic target of cancer remains largely elusive, particularly for its role in cancer immunosurveillance." (PMID 37193698, 2023). "In conclusion, our findings shed light on the molecular mechanism by which the Wnt pathway epigenetically regulates T cell polyfunctionality by upregulating PRMT1 and suggest a potential treatment for enhancing immunotherapy against pathogens and cancer in clinical applications." (PMID 35040433, 2022). "Interestingly, cells from cancer patients showed higher PRMT1 and PRMT6 expression than cells from healthy tissue, which seemed to be beneficial for tumor growth." (PMID 36172281, 2022). "Furthermore, aberrant alternative splicing of PRMT1 has been reported in various cancers, including cervical cancer." (PMID 36144454, 2022). "In addition, PRMT1 is expressed in both the cytosol and the nucleus in renal and pancreatic carcinomas." (PMID 35053470, 2022). "Moreover, molecular modeling led to the discovery of a PRMT1 inhibitor that significantly inhibits the cancer cell lines, HepG2." (PMID 33440687, 2021). "Upregulation of PRMT1 is observed in many cancer types and often correlates with cancer grade and poor patient prognosis, and there are a growing number of studies suggesting that PRMT1 is an important regulator in many pathways that are dysregulated in cancers." (PMID 34688662, 2021). "Finally, the cellular roles and functions of PRMT1, as well as its involvement in cancer, will be addressed." (PMID 34833023, 2021). "Moreover, several cancer-promoting factors, such as Bclaf1, PRMT1, and angiotensin II, have been reported in the transcriptional regulation of HIF-1α." (PMID 33716751, 2021). "In the context of cancer, one recent study showed that in non-MYCN amplified neuroblastoma, low PRMT1 expression was associated with decreased rates of cancer-free survival." (PMID 34688662, 2021). "Finally, we discuss the involvement of PRMT1 in embryonic development, DNA damage repair, as well as its participation in the initiation and progression of several types of cancers." (PMID 34833023, 2021). "Another possible scenario is that a small cancer stem-like subpopulation in sphere cells may present unique vulnerability to PRMT1 inhibition." (PMID 32415090, 2020). "Among the methyltransferases, PRMT1 is the most prevalent arginine methyltransferase in mammalians and is responsible for various processes including lymphocyte function, oxidative stress, inflammation and cancer." (PMID 32357521, 2020). "It is unclear whether PRMT1 inhibitors effects in cancers is due to their functions on splicing, but it is interesting to note that SRSF9 can be methylated by PRMT1, thus affecting its cellular sublocalization." (PMID 32784800, 2020). "Inhibition of PRMT1 is often considered the target for treating cancer cells." (PMID 33273660, 2020). "Furthermore, as an epigenetic regulator, PRMT1 can act as an EMT inducer or repressor in various cancers." (PMID 31655611, 2019). "The dysregulation of PRMT1 is involved in a diverse range of diseases, including cancer." (PMID 31390828, 2019). "Dysregulation of PRMT1 has been observed in several cancer types." (PMID 31043582, 2019). "Therefore, a combined upregulation of PRMT1 and UCP2 as crucial risk in various cancer types, as found in our TCGA analysis, seems to be reasonable." (PMID 29113301, 2017). "On the other hand, the present data suggest that cancer cells in the patient cohort with low levels of UCP2 and PRMT1 might be metabolically less active, yielding attenuated cancer cell proliferation and, thus, increased patient survival." (PMID 29113301, 2017). "Furthermore, analysis via The Cancer Genome Atlas (TCGA) reveals upregulation of both proteins, UCP2 and PRMT1, as common feature of various cancer types." (PMID 29113301, 2017).
cancer (continued). "Therefore, we conclude that protection from mitochondrial Ca2+ overload by a PRMT1-controlled mitochondrial Ca2+ uptake is already a major advantage for cancer cells." (PMID 29113301, 2017). "Thus, UCP2/3 are described as sensitizer of mitochondrial Ca2+ uptake under conditions of increased PRMT1 activity, a phenomenon that has probably great importance in cancer cells." (PMID 27642082, 2016). "By using UCP2/3, cancer cells may be able to counteract the impact of an essential PRMT1 activity to mitochondrial Ca2+ uptake and, thus, re-establish activity of mitochondrial Ca2+ uptake to achieve Ca2+-triggered activation of ATP production." (PMID 27642082, 2016). "The relevance of PRMT1 inhibition in cancer therapies is summarized in reviews." (PMID 26575292, 2015). "Indeed, transactivation of PRMT1 was found in various types of cancer, and inhibition of PRMT1 significantly suppresses growth of cancer cells." (PMID 26460953, 2015). "However, the importance of PRMT1 in the regulation of cancer progression, and metastasis remains incompletely understood." (PMID 25847239, 2015). "Future work will therefore explore whether targeting PRMT1 with drugs could represent an effective treatment for these kinds of cancers." (PMID 26575292, 2015). "Of these signatures, PRMT1 is considered as an ideal target for anti-cancer therapy." (PMID 26460953, 2015). "Moreover, the phenotype of cancer cells after knockdown of PRMT1 is similar to that after knockdown of INCENP." (PMID 26460953, 2015). "Therefore, the complicated functions of PRMT1 deregulation in diverse cancers provide compelling reasons for understanding the detailed dimethylation mechanism catalyzed by this potential drug target." (PMID 23977297, 2013). "Selected cancer and normal colon samples were stained for PRMT1." (PMID 19078953, 2008). "However, the impact of PRMT1 inhibition on DNA damage repair in healthy cells should be investigated during our search for a suitable anti-cancer treatment, as this may affect what type of therapy will be used." (PMID 40001488, 2025). "Therefore, PRMT1 is considered a potential target for cancer treatment." (PMID 39906150, 2025). "However, PRMT1 function is context dependent can be tumor‐suppressive in specific cancer types." (PMID 41256732, 2025). "However, the functional role of PRMT1 in the growth and maintenance of cancer stem cells, including GSCs, remains unclear." (PMID 38474197, 2024). "However, the mechanistic details of PRMT1 dysregulation in cancers are yet to be established." (PMID 39009589, 2024). "PRMT1-mediated methylation of ASK1 may therefore contribute to drug resistance in cancer cells." (PMID 39201539, 2024). "Therefore, we stained adjacent sections for E-cadherin, vimentin, Slug, laminin 5, PRMT1, and PRMT5 and investigated whether the expression levels of these molecules and/or those of MST2 and YAP1 were associated with the cancer cell invasion pattern." (PMID 38444414, 2024). "In addition, the inhibition of PRMT1 using specific small-molecule inhibitors or gene silencing results in cell cycle arrest, proliferation inhibition, and apoptosis induction in several cancer cells, including glioma cells." (PMID 38474197, 2024). "However, how PRMT1 is upregulated in cancer remains poorly understood." (PMID 38839752, 2024). "By dissecting a particular SE-regulated cascade, we have identified PRMT1 as a downstream druggable target that could be used to intercept SE-driven cancers while potentially avoiding some of the severe toxicities that have emerged from other clinical SE-targeted therapies." (PMID 37673892, 2023). "Dysregulation of PRMT1 expression has been consistently identified in diverse human malignancies, including breast, lung, colon, and bladder cancers, as well as leukemia, with extensive research elucidating its regulatory role and substantial prognostic significance in these cancers." (PMID 37627211, 2023).
cancer (continued). "Besides, the role of PRMT1 in metabolic reprogramming of cancer cells remains poorly understood." (PMID 36823188, 2023). "Thus, our data support the notion that PRMT1 may be a key regulator driving cancer progression through regulating multiple signaling pathways in CRC." (PMID 33853662, 2021). "Importantly, such changes were observed not only in tumor proliferation pathways, but also in cancer cell motility and invasiveness pathways, suggesting that PRMT1 inhibition might prevent metastatic progression." (PMID 33208761, 2020). "Therefore, PRMT1 is considered to be a potential target for the treatment of cancer." (PMID 31390828, 2019). "In particular, the negative correlation of survival probability of patients with the expression of UCP2 and PRMT1 supports our hypothesis about the impact of proper mitochondrial Ca2+ uptake on the metabolic efficiency of cancer cells that affects cancer abrasiveness and patient survival." (PMID 29113301, 2017). "Overexpression of PRMT1 may trigger cancer cells to form metastases." (PMID 27556302, 2016). "PRMT1 knockdown, combined with EGFR or KRASG12C inhibitors, decreased persistence and delayed cancer cell regrowth across cell line models and significantly prolonged tumor regression in xenograft models." (PMID 39699269, 2025). "Collectively, these data identify the hypoxia‐PRMT1‐vimentin axis as a critical driver of experimental metastatic progression and position MS023 as a promising therapeutic candidate for targeting cancer metastasis." (PMID 40884268, 2025). "PRMT1 has been found to methylate cGAS and prevent it from dimerizing, which attenuates the cGAS/STING signaling cascade in cancer cells." (PMID 40001488, 2025). "Correspondingly, inhibition of PRMT1 reduces SRSF1 methylation, reverses aberrant splicing patterns, and suppresses cancer cell growth." (PMID 41256732, 2025). "Here, we uncover the pivotal role of the PRMT1/SOX2 axis in regulating cancer stemness, a key factor contributing to cancer chemoresistance." (PMID 41377018, 2025). "Consistently, “DNA-repair” was a significant signature that positively corrected with both PRMT1 and PRMT5 expression levels in cancer cell lines." (PMID 38826355, 2025). "The PRMT1 inhibitor MS023 effectively inhibits METTL14 methylation and markedly reduces its capacity to promote cancer cell proliferation and clonogenicity, suggesting that PRMT1 is pivotal in carcinogenesis through the regulation of METTL14's PTM." (PMID 41256732, 2025). "This underscores the potential of targeting PRMT1 as a means to overcome chemoresistance in TNBC, offering hope for improving treatment outcomes in patients with this difficult-to-treat cancer subtype." (PMID 40927753, 2025). "GlaxoSmithKline (GSK) has found that both the PRMT1 inhibitor GSK3368712 (GSK712) and the PRMT5 inhibitor GSK3326593 (GSK593) have anti-tumor effects in a variety of cancer cell lines, with the exception of HNSCC." (PMID 38709899, 2024). "Our research found that PRMT1 methylates the conserved R133 residue of cGAS, preventing its dimerization and further inhibiting cGAS/STING signaling in cancer cells." (PMID 40018367, 2024). "Our findings demonstrate that PRMT1 significantly promoted cell growth in wild‐type YAP‐overexpressed HCC cells, while exerting marginal impact on cancer cells overexpressing the R124A mutant." (PMID 39367565, 2024). "However, the potential role of PRMT1 in Warburg effect of cancer cells remains largely unknown." (PMID 39009589, 2024). "PRMT1 binds to ATF4 in a BTG1-dependent manner, and PRMT1 methylates ATF4, promoting transcription of some target genes of ATF4, leading to increased apoptosis in cancer cells." (PMID 38326807, 2024). "Therefore, some novel PRMT1 circRNAs that incorporate non-canonical splice sites are likely to disrupt regular gene expression and alter the ratio of normal to pathological transcript variants in a cancer setting." (PMID 37692475, 2024).
cancer (continued). "PRMT inhibitors, particularly those targeting PRMT1 and PRMT5 due to their well-documented role in cancer progression, are being investigated as therapies for hematological malignancies and solid tumors and have progressed to clinical trials." (PMID 39201539, 2024). "Clinical patient samples analysis revealed that the protein levels of PRMT1 and RIP3ADMA were positively correlated in cancer tissues and both of them predicted the longer patient survival." (PMID 37005412, 2023). "A pre-clinical study using a combination of inhibitors of PRMT1 (MS023) and PRMT5 (EPZ015666) demonstrated an efficient anti-cancer effect in lung cancer and pancreatic cancer cell lines." (PMID 37568815, 2023). "In GSE14520, the expressions of PRMT1, PRMT3, PRMT4, and PRMT5 were upregulated in cancer tissues, whereas PRMT2 and PRMT8 were downregulated." (PMID 37627211, 2023). "Here, we report that the protein arginine methyltransferase, PRMT1, methylates cGAS at the conserved Arg133 residue, which prevents cGAS dimerization and suppresses the cGAS/STING signaling in cancer cells." (PMID 37193698, 2023). "In GSE36376, the expressions of PRMT1, PRMT2, PRMT3, PRMT4, PRMT5, and PRMT7 were upregulated in cancer tissues." (PMID 37627211, 2023). "From this, 15 genes were found to be essential in all TNBC cell lines including some of the well-known regulators of cancer cell fitness, such as UHRF1, PELP1 and PRMT1." (PMID 35973998, 2022). "The methyltransferases PRMT1 and PRMT5 have been shown to be overexpressed in many cancers and to regulate cancer cell migration and invasion." (PMID 36555834, 2022). "Considering that PRMT1, PRMT4, and PRMT5 have the highest expression in cancer, their immunosuppressive effect have been well investigated." (PMID 36713412, 2022). "For instance, reports reveal that PRMT1-mediated BRCA1 and c-Myc methylations can regulate cancer cells cell cycle progression and proliferation." (PMID 34775498, 2021). "Based on this rationale, the combination of a PRMT1 inhibitor and PRMT5 inhibitor synergistically inhibits the proliferation of cancer cells with MTAP deletion." (PMID 34006904, 2021). "Hnf4a expression resulted in a decreased expression of cancer-promoting factors LSD1, SETD1A, PRMT1, FOXM1, FAK, and SNAI1, and also an increased expression of CDH1." (PMID 34595169, 2021). "Under conditions of elevated protein methyltransferase 1 (PRMT1), as the case in cancer or aging, UCP2 interacts with PRMT1-methylated MICU1 and re-establishes its Ca2+ sensitivity resulting in a normalization of mitochondrial Ca2+ uptake." (PMID 33614647, 2021). "The highly specific and tunable exogenous control of human PRMT1 could be important in modulating epigenetic factors and post-translational modifications that result in changes in gene expression, particularly with the application to control histone methylation in disease states such as cancer." (PMID 34443661, 2021). "Accordingly, of 949 PRMT-related publications, most have focused on cancer, of which 35% studied PRMT5, 28% PRMT1, and 19% CARM1." (PMID 32743345, 2020). "Among the targets in our chemical probe collection, several have agents currently in clinical trials for cancer (EZH2, EED, DOT1L, PRMT1, and PRMT5) and additional PMT inhibitors are in preclinical studies." (PMID 30604761, 2019). "An interesting finding documented in previous studies is that PRMT1 can induce epithelial to mesenchymal transition (EMT), cellular senescence and apoptosis in various cancer cell types." (PMID 31655611, 2019). "On the other hand, PRMT1 activates RUNX1, that prevents EMT and therefore, RUNX1 serves as a tumor suppressor in various cancers." (PMID 31655611, 2019). "On the other hand, in less advanced carcinomas, we expected frequent RUNX1 expression and co-expression with PRMT1." (PMID 31655611, 2019).
cancer (continued). "Recently, we have shown that PRMT1-driven methylation of MICU1 desensitizes the mitochondrial Ca2+ uptake machinery and, therefore, reduces mitochondrial Ca2+ accumulation in cancer cells." (PMID 29113301, 2017). "In the current study, we identified PRMT1 as a novel regulator of Epithelial-Mesenchymal-Transition (EMT), an essential process during cancer progression, and metastasis." (PMID 25847239, 2015). "In the present study, we show that PRMT1 is an important regulator of epithelial-mesenchymal transition (EMT), cancer cell migration, and invasion, which are essential processes during cancer progression, and metastasis." (PMID 25847239, 2015). "In summary, our study provides a strong evidence for the involvement of PRMT1 in the induction of EMT, cancer cell migration, invasion, and metastasis." (PMID 25847239, 2015). "We have demonstrated that the protein arginine methyltransferase PRMT1 methylates arginine 887 of INCENP, and that this methylation is critically important for the proper chromosomal segregation and cell division of cancer cells." (PMID 26460953, 2015). "Protein arginine methyltransferase 1 (PRMT1), the major arginine asymmetric dimethylation enzyme in mammals, is emerging as a potential drug target for cancer and cardiovascular disease." (PMID 23977297, 2013). "Yet, how PRMT1 is involved in cancer metabolic reprogramming has not been explored, albeit the known role of PRMT1 in metabolic regulation in model organisms." (PMID 40801789, 2025). "Thus, our findings align with existing literature on the pro-immunogenic role of cGAS/STING–IFN signaling and provide mechanistic insight into how PRMT1 loss may enhance anti-tumor immunity without contradicting the broader understanding of inflammation’s dual roles in cancer." (PMID 40858547, 2025). "For instance, PRMT1 methylates HMG box protein 1 (HBP1) at R378, promoting its ubiquitination and degradation, thereby weakening its tumor-suppressive function and enhancing cancer cell proliferation and metastasis." (PMID 41204384, 2025). "Knockdown of PRMT1, which destabilizes FEN1, can induce DNA damage and apoptosis of cancer cells." (PMID 40001488, 2025). "Both genetic and pharmaceutical abrogation of PRMT1 has been shown to promote interferon responses of cancer cells due to lack of H4R3 histone modification." (PMID 40001488, 2025). "In cancer cell lines, overexpression of wild‐type (WT) PRMT1, but not catalytically inactive mutants (E133Q and E142Q), enhanced vimentin R64 aDMA in both HeLa and A549 cells stably expressing Flag‐vimentin." (PMID 40884268, 2025). "MS023 may also inhibit other Type I PRMTs, including PRMT1 and PRMT4, which play roles in RNA splicing, transcriptional regulation, and cancer progression." (PMID 40465651, 2025). "Our findings also demonstrate that PRMT1-catalyzed YAP-R124me2a promotes YAP translocation and may serve as a general biomarker for predicting survival outcomes in cancer patients." (PMID 38653754, 2024). "Recently, increasing studies have been focused on the regulation of Hippo‐YAP signaling in human cancer, however, its regulation by PRMT1‐mediated arginine methylation in HCC has not been reported yet." (PMID 39367565, 2024). "protein arginine methyltransferase 1 (PRMT1) is an important type I protein arginine methyltransferase, which catalyzes the monomethylation and asymmetric dimethylation of arginine and participates in the occurrence and development of a variety of cancers." (PMID 39741976, 2024). "As EGFR-ERK signaling upregulates ZEB1, PRMT1-mediated EGFR upregulation may also contribute to ZEB1 upregulation and ZEB1-mediated cancer stem cell regulation." (PMID 39201539, 2024).